PRKACA (protein kinase cAMP-activated catalytic subunit alpha)
Diseases named in the same sentence as PRKACA in open-access papers (continued):
Sharing a sentence is not in itself a finding about the gene and the disease.
breast carcinoma (18 papers, 2014 to 2025). "The therapeutic significance of PRKACA expression in cancer had previously been suggested by a breast cancer study, which showed that PRKACA mediates resistance to anti-HER2 therapy in breast cancer cell lines via inactivation of BAD and Bcl2-associated death promoter." (PMID 39458904, 2024). "Of note, one recent study suggests that PRKACA expression might be associated with the development of trastuzumab resistance in HER2-positive breast cancer patients." (PMID 36627894, 2022). "In addition to its role in hyperproliferation and inflammation, PRKACA has been associated with drug resistance in breast cancer by supporting the restoration of anti-apoptotic phenotypes of cancer cells." (PMID 34877506, 2021). "An increase in the number of PRKACA transcripts was also observed in hepatocellular carcinoma and breast cancer." (PMID 38201567, 2023). "Among genes identified as differentially methylated between the breast cancer tissue of cases and controls, one of them, PRKACA, was also reported as differentially expressed in two studies included in the review." (PMID 36627894, 2022). "Increased transcription of PRKACA has been detected in patients of breast cancer that resistant to trastuzumab, which becomes a routine treatment for HER2-positive breast cancer." (PMID 35646872, 2022). "Whereas CREB1 was found to reduce the apoptosis process and increase cell proliferation in breast cancer, PRKACA plays a key role in tumorigenesis and development of BC." (PMID 33910530, 2021). "Co-phosphorylation analysis suggests strong correlation between the behaviour of SGK1 substrates and S330 in the ovarian cancer cell line while PRKACA annotated substrates track S330 more closely in the breast cancer models." (PMID 30811403, 2019). "Indeed, elevated PRKACA expression was found in trastuzumab-resistant breast cancer patients, evidence that PRKACA is activated in trastuzumab-resistant breast cancer cases." (PMID 39458904, 2024). "One of the most differentially methylated genes, PRKACA, has been reported to be differentially expressed in breast cancer tissues of trastuzumab-resistant compared to trastuzumab-sensitive HER2-positive breast cancer patients in two studies included in our systematic review." (PMID 36627894, 2022). "Moreover, CREB1 was found to reduce the apoptosis process and increase cell proliferation in breast cancer; whereas, PRKACA plays a key role in tumorigenesis and development of BC." (PMID 33910530, 2021). "Moreover, PRKACA mediates apoptosis-related signaling pathways in many cancer diseases, such as breast cancer and follicular thyroid cancer cells." (PMID 30029622, 2018). "Protein kinase cAMP-activated catalytic subunit alpha (PRKACA)-mediated phosphorylation of MORC2 on T582 abrogates CMA-mediated degradation of MORC2, leading to endocrine resistance of breast cancer cells." (PMID 36694209, 2023). "PRKACA is one of the catalytic subunits of protein kinase A and was found to mediate resistance to HER2-targeted therapy in breast cancer." (PMID 36823654, 2023). "PRKACA belongs to the PKA signaling pathway; an elevated expression of PRKACA can regulate HER2-targeted therapy in breast cancer cells through the inactivation of the pro-apoptotic protein BAD." (PMID 35741587, 2022). "The inferred subset GRN from the MCF7 breast cancer cell line highlights that the GM2A and PRKACA genes are activated and suppressed by several genes." (PMID 33168813, 2020). "With regards to drug sensitivity/resistance, PRKACA is over expressed in invasive and anti-HER2 therapy (trastuzumab/ lapatinib)-resistant breast cancers." (PMID 29686393, 2018). "Although we identified very few genes that overlap between studies, our review suggests that some of the genes acting in the PI3K pathway, such as PRKACA, might play an important role in developing resistance to anti-HER2 agents in breast cancer patients." (PMID 36627894, 2022).
Cushing syndrome (17 papers, 2015 to 2025). Cushing's syndrome (CS) encompasses a group of hormonal disorders caused by prolonged and high exposure levels to glucocorticoids that can be of either endogenous (adrenal cortex production) or exogenous (iatrogenic) origin. "A hotspot somatic PV (L206R) in PRKACA is the most frequent cause of cortisol-producing ACAs, which leads to Cushing’s syndrome." (PMID 41106389, 2025). "Pathogenic somatic variants of PRKACA often manifest as endocrine and metabolic disorders such as Cushing’s syndrome, cortisol-producing adenomas (CPA’s), hypothalamic hamartomas, and cardiac myxomas." (PMID 38481146, 2024). "This is highlighted by the prevalence of Cushing’s Syndrome and acrodysostosis for patients with PRKACA or PRKAR1A variants, respectively." (PMID 38481146, 2024). "PRKACA mutation (PRKACA mt) in CPA patients was reported to be associated with more pronounced clinical manifestation of Cushing’s syndrome." (PMID 35216289, 2022). "Benign adrenal cortical tumors presenting with Cushing syndrome often have diverse mutations (PRKACA, PRKAR1A, GNAS, PDE11A, and PDE8B) involving the cyclic AMP signaling pathway." (PMID 29594118, 2018). "A recent study has broadened our knowledge of pathogenic PRKACA alterations in bilateral micronodular adrenocortical disease presenting with Cushing syndrome." (PMID 29594118, 2018). "Hotspot mutation L206R in PRKACA, which encodes the catalytic subunit of cyclic-adenosine-monophosphate-dependent protein kinase, was previously reported in adrenocortical adenomas associated with corticotropin-independent Cushing’s syndrome." (PMID 35966080, 2022). "L206R mutation of PRKACA in ACA-S was associated with more severe phenotypes (Cushing’s syndrome)." (PMID 26106367, 2015). "Mutations in PRKACA (the PRKACB paralogue) and GNAS are mutually exclusive in Cushing’s syndrome and result in similarly sized adrenocortical adenoma diameter and similar increases in serum cortisol." (PMID 39342354, 2024). "Adrenocortical adenomas that cause Cushing’s syndrome develop as a result of mutations in PRKACA, the gene encoding protein kinase cAMP-activated catalytic subunit alpha (PKA C-alpha)." (PMID 38034011, 2023). "Besides, immunohistochemical staining for CYP11B1 and PRKACA analysis did not support the diagnosis of Cushing's syndrome." (PMID 33013693, 2020).
adrenocortical adenomas (15 papers, 2015 to 2025). "Further investigation revealed that both diseases were caused by KCNJ5 and PRKACA mutations found in the bilateral adrenal adenomas." (PMID 39375255, 2025). "Somatic activating mutations of PRKACA are the most common molecular alterations (around 40%; range, 23–57%) in glucocorticoid-producing adrenal cortical adenomas." (PMID 29594118, 2018). "Adrenal adenomas harboring mutations in PRKACA or GNAS are generally smaller and present with more overt hypercortisolism than the non-mutant types." (PMID 27606678, 2016). "Somatic mutations of PRKACA have been detected in adenomas of the adrenal cortex." (PMID 30029622, 2018). "In adrenal gland adenomas GNAS SWI arginine and p.L207R mutations in the cAMP activated enzyme PRKACA are mutually exclusive." (PMID 31337866, 2019). "PRKACA copy number gain was found in the germline of several patients with cortisol-producing BAH, whereas the somatic Leu206Arg (c.617A>C) recurrent PRKACA mutation was found in as many as half of all adrenocortical adenomas associated with AICS." (PMID 26042218, 2015). "PRKACA mediates PKA activation, which triggers steroidogenesis, and is involved in adrenocortical pathologies with ACTH-independent hypercortisolism, such as adrenocortical adenomas, carcinomas, or bilateral adrenocortical hyperplasias." (PMID 37478183, 2023).
hepatocellular carcinoma (11 papers, 2014 to 2025). A malignant tumor that arises from hepatocytes. "Background/Objectives: PRKACA alterations have clear diagnostic and biological roles in the fibrolamellar variant of hepatocellular carcinoma and a potential predictive role in that cancer type." (PMID 39458904, 2024). "Regarding protein kinase A catalytic subunit alpha (PRKACA), it mediates SIK inactivation and CRTC2-p300–driven transcription, processes linked to hepatocellular carcinoma growth." (PMID 40600138, 2025). "The tumor-promoting activities of the PRKACA and PKA signaling have been described for classic and fibrolamellar variants of hepatocellular carcinoma, and breast, prostate, ovarian, and non-small cell lung cancers, glioblastoma, astrocytoma, and leukemia." (PMID 39458904, 2024). "Many studies have shown that PRKACA is crucial to the development and progression of a variety of cancers, and also that it can be used as a biomarker for hepatocellular carcinoma." (PMID 34837692, 2021). "On the first tissue microarray, all of the 88 conventional hepatocellular carcinomas were negative for PRKACA rearrangements, as were samples of non-neoplastic liver that were either normal (N=7) or showed fatty change (N=6)." (PMID 28862261, 2018). "In addition, 88 conventional hepatocellular carcinomas were evaluated with PRKACA FISH and all were negative." (PMID 28862261, 2018).
lung carcinoma (7 papers, 2013 to 2024). "Second, the systemic levels of PRKACA have been observed to be elevated in patients of various types of cancers, including lung cancer, and thus PRKACA in blood has been proposed as a potential cancer biomarker." (PMID 37298489, 2023). "Previously, the PKA catalytic subunit alpha (PRKACA) was identified as the dominant catalytic subunit that is expressed and active in lung cancer; it is reported to be essential for tumor development and growth." (PMID 36209131, 2022). "PRKACA involves in lung cancer epithelial–mesenchymal transition, migration, and invasion." (PMID 26735889, 2016). "Finally, in A549 lung cancer cells it was shown that long-term (2 days) hypoxic incubation can increase the relative expression of PRKACA, indicating that this may occur independently of HIF-1α transcriptional regulation." (PMID 32111982, 2020). "It was also estimated that as PRKACA was a tumor target, it might be helpful as therapy, but due to the lack of evidence, its involvement in the development of lung cancer is debatable." (PMID 35256890, 2022).
Adrenocortical tumors (5 papers, 2015 to 2025). "More recently, mutations of PRKACA, the gene coding for the catalytic subunit C alpha (Cα), were also identified in the pathogenesis of adrenocortical tumors." (PMID 26042218, 2015). "Although cortisol-producing adenomas (CPAs), a leading cause of adrenocortical tumours, are mostly caused by somatic mutations in genes such as GNAS or PRKACA, how CPAs arise from a precursor lesion with genetic mutations in adrenocortical tissues remains to be elucidated." (PMID 38570222, 2024).
COVID-19 (5 papers, 2020 to 2024). A disease caused by infection with severe acute respiratory syndrome coronavirus 2. "Obvious nsp13:PRKACA and nsp13:CREB1 association signals (shown in red) were observed in COVID-19 autopsy lung tissues, as well as in mouse-adapted SARS-CoV-2-infected mouse lung tissues." (PMID 38445884, 2024). "Among the significantly up- or down-regulated proteins in COVID-19 patient urine, metallothionein-1G, lipoprotein lipase, β2M, PRKACA, FOLR2, and APOA4, showed significant changes compared to both healthy controls and non-COVID-19 pneumonia cases." (PMID 33203833, 2020). "A decrease in the expression of the following genes was also observed in COVID-19-positive patients: RAPGEF1 (p = 0.0091), MAP2K1 (p = 0.038), CEBPB (p = 3.3 × 10−6), STAT6 (p = 0.041), JUN (p = 1.4 × 10−8), PRKACA (p = 0.021), and AKT1 (p = 1.3 × 10−6)." (PMID 36298734, 2022).
depression (5 papers, 2019 to 2025). "Therefore, the prolonged oxidative stress led to increased PDE4 which in turn decreased CERB, PRKACA and BDNF and increased IL-6, enhancing neuronal susceptibility to injury and development of depression." (PMID 38315652, 2024). "In this module, ADCYAP1R1, PRKACA, MAPK8, MAPK14, GRIA1, and FOS are both targeted genes of CGFC and pathogenic genes of depression; RHOA is a specific targeted gene of CGFC, and most of these genes are related to the pathogenesis or treatment of depression." (PMID 34867413, 2021). "This study investigated the effects of roflumilast (PDE4 inhibitor) on the activity of the PRKACA-CREB-BDNF signaling pathway, pro-inflammatory cytokine production and change in hippocampal histology in male Wistar rats exposed to CRS model of depression." (PMID 38315652, 2024). "PPI network analysis identified core targets such as MAPK3, STAT3, AKT1, PRKACA, MAPK1, and TNF, suggesting BCBL's efficacy in depression treatment may stem from its action on multiple key targets." (PMID 40909251, 2025).
glioma (5 papers, 2021 to 2022). A benign or malignant brain and spinal cord tumor that arises from glial cells (astrocytes, oligodendrocytes, ependymal cells). "PRKACA was identified to be PRG and used to construct prognostic risk prediction models in colon adenocarcinoma and glioma." (PMID 36127654, 2022).
melanoma (5 papers, 2018 to 2025). A malignant, usually aggressive tumor composed of atypical, neoplastic melanocytes. "Supporting this, the adenyl cyclase gene, ADCY9, and the PKA catalytic subunit alpha (PRKACA) were identified as key resistance effectors in melanoma, with PRKACA displaying the highest rescue score among serine/threonine kinases in a gain-of-function resistance study." (PMID 40719625, 2025).
schizophrenia (5 papers, 2011 to 2020). A major psychotic disorder characterized by abnormalities in the perception or expression of reality. "In addition, PRKACA contained cluster which involved neurotransmission related functions may be relevant to the pathophysiology of schizophrenia." (PMID 25522158, 2014). "TRAF6, PRKACA and ACTN1 are all connected to both SRC and PSEN1 and therefore it might be useful to further investigate their interactions in order to better understand the mechanisms that could be involved in Schizophrenia." (PMID 32735660, 2020).
prostate carcinoma (4 papers, 2017 to 2025). A carcinoma that arises from epithelial cells of the prostate gland. "Meanwhile, this subnetwork also captured 12 prostate cancer-related genes with a novel NTKG of PRKACA." (PMID 34131148, 2021). "A preclinical study demonstrated that crotonylation of PRKACA enhances the activity of PKA and thereby promotes colorectal cancer development via the PKA-FAK-AKT pathway, whereas PRKACA is secreted by prostate cancer cells." (PMID 39458904, 2024).
adrenal cortical carcinoma (3 papers, 2018 to 2023). "PRKACA gene defects can lead to adrenal cortical carcinoma, but PRKACA is not directly related to pyrosis." (PMID 36911522, 2023).
adrenal hyperplasia (3 papers, 2015 to 2025). "Among these are somatic mutations of PKA catalytic subunit alpha gene (PRKACA) in ACA, germline, and somatic mutations of armadillo repeat containing 5 gene (ARMC5) in primary bilateral macronodular adrenal hyperplasia and somatic alterations of the E3 ubiquitin ligase gene ZNRF3 in ACC." (PMID 26106367, 2015).
bladder cancer (3 papers, 2022 to 2023). "However, the molecular mechanism of PRKACA involved in the occurrence and development of bladder cancer is still unclear and needs to be investigated and explored in depth." (PMID 36569221, 2022). "The Univariate Cox regression analysis revealed that eight PRGs (PRKACA, GSDMB, CASP9, GSDMD, CASP6, CASP8, AIM2, and CASP1) were significantly correlated with the prognosis in bladder cancer." (PMID 36120583, 2022).
colorectal cancer (3 papers, 2014 to 2025). A primary or metastatic malignant neoplasm that affects the colon or rectum. "However, the predominant regulatory mechanisms that better predicted PRKACA expression in our gastric and colorectal cancer cohorts are epigenetic, transcriptional, and microRNA regulatory mechanisms." (PMID 39458904, 2024). "Additionally, post-translational modifications, such as the crotonylation of PRKACA, enhance PKA activity and drive colorectal cancer development through the PKA-FAK-AKT pathway." (PMID 40699738, 2025). "However, the roles of PRKACA have not been comprehensively examined in gastric and colorectal cancers (GC and CRC)." (PMID 39458904, 2024).
liver fibrosis (3 papers, 2020 to 2025). "Furthermore, it has been previously documented that 1-PHE and LDL-receptor-related protein 5, as well as protein kinase cAMP-activated catalytic subunit alpha, have binding scores of ligands and target proteins of liver fibrosis." (PMID 40649803, 2025). "This suggests that PRKACA may play a significant role in the development and progression of hepatic fibrosis." (PMID 39062514, 2024).
adrenal tumors (2 papers, 2016 to 2022). "Overall, immunohistochemical analysis revealed higher expression of StAR in adrenal tumors with mutations in PRKACA, GNAS, and PRKAR1A than in wild-type tumors, which exhibited lower expression of StAR." (PMID 27606678, 2016). "Somatic mutations that constitutively activate WNT/β-catenin (CTNNB1), G-protein (GNAS, GNAQ, GNA11), and cAMP/protein kinase A (PKA) (GNAS, PRKACA) signaling can drive unrestrained cell proliferation and survival in diverse tumors, including adrenal tumors." (PMID 36004349, 2022).
dilated cardiomyopathy (2 papers, 2013 to 2021). Cardiomyopathy which is characterized by dilation and contractile dysfunction of the left and right ventricles. "Therefore, the present study also for the first time reported ferroptosis related gene CDKN1A and pyroptosis related gene PRKACA may be involved in the development and progression of dilated cardiomyopathy." (PMID 34970603, 2021). "Among the remaining 19 DEGs, IGF1 (NO.17), MYL2 (No. 31), PCK1 (No. 33) and PRKACA (No. 39) were involved in the pmAF – related PPAR signaling pathways, focal adhesion and dilated cardiomyopathy." (PMID 24204599, 2013).
gastric cancer (2 papers, 2023 to 2024). A primary or metastatic malignant neoplasm involving the stomach. "A total of 20 PRKACA promoter methylation loci and their beta values were retrieved from the gastric cancer methylation data." (PMID 39458904, 2024). "The results of the analyses suggest that PRKACA may be a pro-migration/invasion and anti-proliferation gene in gastric carcinogenesis and gastric cancer progression." (PMID 39458904, 2024). "Some kinases (e.g. PRKACA, CSNK2A1 and MAPK1) were found specifically dysregulated across multiple tumour types, but more than half were dysregulated in just one tissue (68%) such as MYLK kinase in stomach cancer and MTOR in kidney cancer." (PMID 36688815, 2023).
ischemic stroke (2 papers, 2022 to 2024). A stroke disorder caused by obstruction of blood flow to the brain, due to thrombotic (local blood clot formation) or embolic (due to a blood clot or other material traveling from another site) event. "Interestingly, in acute MI and ischemic stroke, the expression of APAF1 and IRAK3 was negatively correlated with the abundance of NK cells, while the expression of ATM, CAPN1, IL1B, IL1R1, PRKACA, PRKACB and TNFRSF1A was positively correlated with the abundance of NK cells in MI." (PMID 38526027, 2024). "Interestingly, APAF1 and IRAK3 expression correlated negatively with NK cell abundance in both acute myocardial infarction and ischemic stroke, whereas ATM, CAPN1, IL1B, IL1R1, PRKACA, PRKACB, and TNFRSF1A correlated negatively with NK cell abundance in acute myocardial infarction." (PMID 35432334, 2022).
ovarian carcinoma (2 papers, 2019 to 2023). A malignant neoplasm originating from the surface ovarian epithelium. "However, some PYAGs with CNV gain, such as GSDMD, TP63, PRKACA, PJVK and CASP4, showed downregulated mRNA expression in ovarian cancers, and some PYAGs with CNV loss, such as IL18, GPX4, GZMA, NLRP6 and CASP6, showed upregulated mRNA expression in ovarian cancers." (PMID 36707884, 2023).